TNF (tumor necrosis factor)
Diseases named in the same sentence as TNF in open-access papers (continued):
Sharing a sentence is not in itself a finding about the gene and the disease.
infection (continued). "In fact, robust activation of T cells by AMs was associated with worse clinical outcomes during infection with SARS-CoV-2 in a manner that was dependent on both IFN-γ and TNF." (PMID 38345473, 2024). "Following the infection of macrophages and nanomaterial co-cultures by C. albicans, we evaluated IL-1β, IL-6 and TNF-α transcription levels using RT-qPCR." (PMID 39407477, 2024). "In general, medical literature offers evidence that TNF synergizes with interferon, and since the action of these molecules is extremely important in clearing the infection, it is mandatory to screen patients before starting anti-TNF agents." (PMID 38979406, 2024). "After 48 h post-infection, the gene expression of IL-1β and TNF-α expression significantly decreased compared with 3-h post-infection." (PMID 38965554, 2024). "Contrary to other infections with intracellular microorganisms, during acute disease, TNF-α production favors the spread of S. Typhimurium in mice." (PMID 38533492, 2024). "Using qPCR, we evaluated the expression of cytokines that are important for neutrophil recruitment to sites of infection, including IL1β, IL-6 and TNFα, as well as the neutrophil chemokines CXCL1 and CXCL2." (PMID 39509414, 2024). "Upon infection, IL-4+ cells decreased precipitously, giving rise to increased levels of the Th1 inflammatory cytokines TNF-α and IFN-γ." (PMID 38814732, 2024). "It induces the aggregation of immune cells, including neutrophils and macrophages, at infection sites, leading to the release of IL-1, IL-6, and TNF-α, promoting inflammation." (PMID 39686447, 2024). "This response is characterized by the secretion of proinflammatory cytokines and chemokines such as tumor necrosis factor-alpha (TNF-α), interleukin-1 (IL-1), and interferons (IFNs), which recruit and activate other immune cells to the site of infection." (PMID 38673507, 2024). "A statistically significant reduction in IL-1β levels in culture supernatants was seen 24 hours post-infection with AN_CH_37, as well as other pro-inflammatory cytokines, namely IL-6 and TNF-α." (PMID 38590438, 2024). "Similar to ROSS strain infection, the expression of TNF-α, IL-6, CCL-2, and IL-10 was reduced upon etravirine treatment compared with DMSO treatment under the LR2006 OPY1 strain challenge." (PMID 39339151, 2024). "Given that granulocytes are the predominant cellular infiltrate in the galea and bone flap during craniotomy infection and are in close proximity to the biofilm, we next explored the potential mechanism responsible for TNF-dependent granulocyte recruitment." (PMID 39044282, 2024). "These cells generate cytokines such as IFN-γ and TNF-α in response to infection, thus activating macrophages to eliminate M tuberculosis." (PMID 38968531, 2024). "Here, TNFα was shown to synergistically boost the HIV-1 transcription in the early stages of infection by the TNF-mediated translocation of NF-κB." (PMID 38932230, 2024). "One day after treatment, a weak positive expression of TNF-α was detected in the epithelial and vascular endothelial cells of the treatment groups, with lighter staining compared to the infection group." (PMID 38708351, 2024). "A balance between TNF-α and IL-10 concentrations is crucial for controlling infection within a single granuloma." (PMID 39650648, 2024). "In our studies, we also observed an increased level of the main mediator of tissue damage, TNF-α, during infection, but only in the GI.1 group (5.7-fold change, p = 0.006 vs. control)." (PMID 39273479, 2024). "TNF‐α, a cytokine predominantly secreted by monocytes, macrophages, and dendritic cells upon infection with Mtb, is essential for granuloma formation and activates macrophages with immunoregulatory properties." (PMID 39240051, 2024).
infection (continued). "During natural infection with adenovirus, pro-inflammatory cytokines, such as IL-6 and TNF-alpha, are released." (PMID 39508450, 2024). "The infection triggers an inflammatory response characterized by the release of cytokines such as IL-6 and TNF-alpha, which recruit immune cells to the infection site." (PMID 39125464, 2024). "Compared to the control group, the expression levels of IL-1β, IL-6, and TNF-α in the PCV4-inoculated group continuously increased during the infection period, peaking at 21 days." (PMID 39135875, 2024). "IL-1β promotes the production of other proinflammatory cytokines, such as TNF-α and IL-6, and induces the expression of adhesion molecules and chemokines, which attract immune cells to the site of injury or infection." (PMID 38397895, 2024). "After 7 days of infection, the levels of Th1 cytokines IFNγ, IL-6, and TNFα were elevated in the BALF, but these levels were significantly reduced in TLR7 KO mice." (PMID 39769461, 2024). "Studies have shown that the TNF signaling pathways trigger an inflammatory response and mediate resistance to infection by L. major." (PMID 38190401, 2024). "Mice sacrificed at 12 weeks post-infection showed an increase in their blood TNFα levels after the DSS+Nocardia treatment." (PMID 38542396, 2024). "Particularly noteworthy is the significant contribution of pro-inflammatory cytokines IL-1β (manifesting from the 20th day post-infection) and TNF-α (evident from the 10th day post-infection) to the worsening of neuropathology." (PMID 39766497, 2024). "To investigate the impact of MNK1 knockout on pro-inflammatory cytokine production in J774A.1 cells during Vv infection, we compared the levels of TNF-α and IL-6 in parental and MNK1−/− cells infected by Vv." (PMID 38980024, 2024). "Already at day one post-infection, high frequencies of IFNγ-, TNFα- and granzyme B (GrzB)-producing CD8+ T-cells were detectable reaching the maximum at day one or three post-infection before declining." (PMID 39472590, 2024). "Infection is a significant concern among patients receiving infliximab, an anticipated adverse event given the mechanism of TNF‐alpha inhibition." (PMID 38087813, 2024). "It has to be noted that the initial response of the innate immune system to injury and infection is reflected by TNF-α and IL-6." (PMID 39200283, 2024). "On days 5 and 7 after infection, aPKC-deficient T cells had the same levels of T-bet GZMB, Tumor necrosis factor-alpha (TNFa), and IFNγ as wild-type (WT) cells but lower levels of Eomes, Bcl2, and IL-2." (PMID 38495874, 2024). "In L. braziliensis, EV‐primed macrophages showed increased production of IL‐1β, IL‐6, IL‐10 and TNF‐α upon infection, suggesting a role of EVs in exacerbating inflammatory responses." (PMID 39113589, 2024). "Other upregulated pathways include pathways in cancer, TNF signalling pathway, complement and coagulation cascades, chemokine signalling pathway, immunity pathway, and viral interaction/infection related pathways." (PMID 38195813, 2024). "High levels of TNF-α, IL-1β and IL-6 and MDA in the SE-stimulated mice indicated that SE infection caused an imbalance in the redox status, resulting in oxidative stress and inflammatory responses." (PMID 39456517, 2024). "PA14 infection induced significant increases in IL-6, TNF and IL-1β in the PA14 + PBS group compared to the Control + PBS group in both lung and BALF." (PMID 39062025, 2024). "The literature data are still debatable concerning the precise mechanism of endocan expression in infection, but it is clear that its in vitro expression is stimulated as a result of TNF-α or IL1-β." (PMID 38474287, 2024). "CRP and TNF-α are inflammatory biomarkers that are elevated in response to infection or inflammation." (PMID 39182041, 2024).
infection (continued). "Chronic wounds are generally characterized by a nonmigratory and hyperproliferative epidermis, the presence of infection with biofilm formation and unresolved inflammation, exhibiting elevated levels of pro-inflammatory cytokines, like TNF-a." (PMID 39335054, 2024). "IL-6 and TNF-α are typical cytokines secreted by M1 macrophages; in the early stage of infection and tissue injury, IL-6 and TNF-α were rapidly produced to stimulate the immune response." (PMID 38731567, 2024). "Here, we observed higher TLR2, TLR4, TLR5, TLR6, TLR8, TLR9, Myd88, NLRP3, ASC, and TNF-α mRNA expression at seven weeks after infection by S. mansoni in BALB/c and C57BL/6 mice compared to Swiss mice." (PMID 38896633, 2024). "TNF is produced by a wide range of immune and parenchymal cells within minutes following injury or infection." (PMID 39044282, 2024). "After infection, we noted heightened TNF-α levels in the respiratory tract of mice pre-treated with Cp 090104 or CP-derived BLPs, while in sera it was markedly lower than in the control group." (PMID 38675794, 2024). "In rat neuronal cells cultured in vitro, it has been observed that, in response to EV infection, both microglia and astrocytes can induce an inflammatory response through the secretion of NO, TNF-α, and IL-1β." (PMID 38248274, 2024). "NK cells are crucial in the innate response against the parasite because they produce IFN-γ and TNF-α, and these cytokines will lead to the elimination of T. cruzi by inducing the activation of macrophages in the early phase of infection." (PMID 39452741, 2024). "In an established in vitro system that mimics blood stage infection, elevated proinflammatory TNF and IL-6 cytokine production is correlated with increased mono- and tri-methylated H3K4 levels." (PMID 38316918, 2024). "Cytokines are a response to infection, and the main cytokines involved in sickness responses are the pro-inflammatory cytokines IL-1 and TNF-α." (PMID 39066248, 2024). "In particular, the TNF-α, IL-1β, and IL-6 levels increased by around 18-, 11-, and 13-fold, respectively, at 24 h post-infection and by around 23-, 22-, and 21-fold, respectively, at 48 h post-infection compared to uninfected PAMs." (PMID 38664855, 2024). "A second study examined infection using the attenuated C. posadasii strain 1038 in the setting of TNF inhibition." (PMID 38667927, 2024). "Inflammatory cytokines, such as tumor necrosis factor-α (TNF-α) and interleukin-1 (IL-1), are produced in response to infection, tissue damage, or immune triggers." (PMID 38088444, 2024). "The risk of infection is higher among patients who are taking biological agents like Janus-associated kinase (JAK-2) inhibitors, tumor necrosis factor alpha inhibitors, and long-time steroids." (PMID 38406079, 2024). "These cytokines are known mediators of inflammation in the context of L. pneumophila infections, and IL-6 and TNFα are highly induced upon infection with the L. longbeachae ΔdotB mutant." (PMID 39259722, 2024). "Upon infection, TNF-α is released by macrophages and monocytes to stimulate inflammatory pathways and oxidative stress." (PMID 38731913, 2024). "KEGG analysis indicated that these DEGs were enriched in several immune-related pathways, including pathogen infection, natural killer cell-mediated cytotoxicity, IL-17 signaling, and TNF signaling pathways." (PMID 39717623, 2024). "The higher the expressions of MIR155HG (r=0.623; P<0.05) and TNF-α (r=0.431; P<0.05) are, the higher the incidence rates of infection, renal damage and cardiac damage will be." (PMID 38699702, 2024). "The levels of pro-inflammatory cytokines such as IL-1α, IL-1β, IL-2, IL-6, IL-12, IL-17, INFγ, and TNFα increased in the serum of mice infected with fungal strains from a very early stage (3 h) to 7 days post infection." (PMID 38783167, 2024).
infection (continued). "For example, leukocyte recruitment to the liver and spleen was impaired in TB-infected TNF KO mice up to day 14 post-infection, with recovery to (and sometimes exceeding) WT levels at day 28, identical to the time frames presented in the current study." (PMID 39044282, 2024). "At 24 h post-infection, both berbamine and tetrandrine significantly reduced TNF-α, IL-1β, and IL-6 levels compared to the ASFV control by around 60–80%." (PMID 38664855, 2024). "Analysis of cytokines indicated a global PCLS age-effect and PAO1 infection-effect for CXCL1, IL-6, and IL-1β, while for TNF-α only a global infection-effect was observed." (PMID 38178102, 2024). "Pro-inflammatory cytokines, such as IL-6 and TNF-α, help to initiate the inflammatory response necessary to control infection and prevent its systemic spread." (PMID 37662481, 2023). "In general, the expression of IL-1β is induced by the presence of stressful stimuli such as hypoxia, inflammation, infection, which induces toll-like receptors (TLRs) to stimulate tumor necrosis factor (TNF)." (PMID 37511306, 2023). "The serum results showed that IL-6 and TNF-α significantly increased after CsA infection (p < 0.01)." (PMID 37764093, 2023). "TNF is produced by multiple innate immune cell types and T cells after infection and plays pleiotropic roles in controlling infection in tissues such as the spleen and liver." (PMID 36950118, 2023). "The pro-inflammatory cytokines (Th1 immune response) (IL-1, IL-2, IL-6, IL-8, IL-18, IFN-γ, and TNF-α) generally regulate growth, cell activation, differentiation, and homing of the immune cells to the infection sites." (PMID 38133693, 2023). "Quantitative analysis of protein levels performed by dot blot scanning showed that the expression levels of ACE-2, annexin-V, flotillin-1, TLR-7, LAMP, TNF-α, caspase-1, caspase-8, and others were altered in EVs after infection." (PMID 36979955, 2023). "Regarding cytokine production, ELISA analysis further demonstrated that both cKp and hvKp infection greatly enhanced the release of IL-6, TNF-α, and IL-1β in macrophages." (PMID 37223846, 2023). "The inflammatory response of MIO-M1 cells to infection with Mon601 was characterized by elevated expression of tumour necrosis factor (TNF)-α, interleukin (IL)-1β, and IL-6 (p < 0.01) compared to uninfected control cells." (PMID 37515098, 2023). "Compared with the parental virus ASFVWT, ASFVΔI10L infection consistently and remarkably enhanced the phosphorylation levels of IKKβ and the K63-linked ubiquitination of NEMO upon TNF-α treatment." (PMID 37607059, 2023). "An increased number of activated macrophages producing TNF-α (IBA1+ TNF-α+ cells) was observed in the lungs during the acute stage of infection (4 dpi), and to a lesser extent during recovery from the infection (16 dpi)." (PMID 37854602, 2023). "Further investigation demonstrated that apoE23 reduced plasma TNF-α, IL-6, and LPS levels; decreased bacterial load in spleen tissue; and attenuated infection-induced lung, liver, and small intestine injuries in septic mice." (PMID 37533741, 2023). "Briefly, immune responses induced by HuN4 and SD53-1603 infections shared some similarities, such as the elevation and recovery of IL-1β, TNF-α, and IFN-γ levels." (PMID 37920268, 2023). "The mRNA levels of interleukin-1β (IL-1β) and tumor necrosis factor alpha (TNF-α) significantly change in response to bacterial infections, indicating their association with other immune-related molecules in fish during infections." (PMID 37569767, 2023). "By utilizing TNF-α to establish the corresponding model, the early infection-induced inflammation was created to evaluate quercetin’s preventive and therapeutic effects on inflammation." (PMID 38050310, 2023). "TNF-α is an endogenous alarm signal, which drives inflammatory responses in injury or infection to recruit other immune cells to evoke an immune-stimulatory cascade." (PMID 37189133, 2023).
infection (continued). "We observed that expression of inflammatory chemokine CCL2 and cytokine TNF-α increased in the brain of Irf7−/− during the course of infection." (PMID 37737190, 2023). "The produced cytokines, tumor necrosis factor (TNF), interleukin 6 (IL-6), and interleukin 1 (IL-1), also trigger local cellular responses to injury or infection and fever development." (PMID 36865749, 2023). "Production of cytokines and cells of innate immunity: Neutrophils and macrophages are the main cells involved in the fight against the parasite, while IL-8, IL-6 and TNF-α are the most produced cytokines in response to this infection." (PMID 37125086, 2023). "The TNF threshold (tao.TNF) is positively correlated with total bacteria, since a lower threshold means more macrophages are recruited into the infection thus lowering the total bacterial load." (PMID 40809472, 2023). "In mouse melioidosis with neurological symptoms, pro-inflammatory cytokine levels of IL-6 and TNF-α were relatively high during early infection, but later the level of TNF-α was decreased." (PMID 38001928, 2023). "They found that tautomerase null mice had lower TNF-α and neutrophil levels and a lower bacterial load after infection." (PMID 38275363, 2023). "IFN-1, a prominent inhibitor of tumorigenesis and promoter of apoptosis, has been observed to be upregulated in patients with severe infection with TNF and IL-1 to drive inflammation and contribute to worsening infection." (PMID 37055774, 2023). "Garre suggested the highlight CX3CR1high monocytes and TNF-α as potential therapeutic targets for preventing infection-induced cognitive dysfunction." (PMID 37179331, 2023). "During early infection, TNFα, IL-1α, IL-6 and IL-8 are produced and result in stimulation of local and systematic pro/anti-inflammatory responses." (PMID 36726139, 2023). "MiR-155 host gene transcription is upregulated by a variety of factors R848 and TNF in addition to infection by HIV-1." (PMID 36766808, 2023). "UC medications, including chronic corticosteroids and agents modulating tumor necrosis factor (TNF), interleukins (IL), or Janus kinases (JAK), are known to increase the risk of infection due to their immunosuppressive effects." (PMID 37207089, 2023). "Among these factors, TNF-α is a key regulator of the inflammatory response, and its level is correlated with the severity of infection and inflammatory response in serum and tissues." (PMID 36872332, 2023). "On the other way, SP-treated cells displayed suppressed production of TNF-α and IL-6 at all time points tested and 48 h post-infection, respectively." (PMID 37280772, 2023). "TNF-α gene was significantly upregulated in branchial tissue at all-time points, particularly at day 14 (~ threefold, P < 0.0001) post-infection compared to the control." (PMID 37337042, 2023). "The mRNA expression of pro-inflammatory cytokines, including IL-1β, IL-6 and TNF-α were significantly higher in the infection group than that in the control and nisin group (P < 0.05)." (PMID 37803465, 2023). "Using this priming and infection model alongside genetic tools, we demonstrate that TNF signaling through TNFR1 licenses L. pneumophila-infected cells to rapidly and robustly undergo cell death independently of flagellin and the NAIP/NLRC4 inflammasome." (PMID 37279255, 2023). "To mimic this endogenous TNF produced following initial infection and subsequent restriction, we primed cells with recombinant TNF (rTNF) for 16 hours prior to infection." (PMID 37279255, 2023). "Specifically, 2 weeks after infection, we observed higher levels of some cytokines involved in Th1 (TNF-α) and Th17 (IL-6 and IL-17) in the lungs of anti-Gr1-treated mice compared with those in the IgG2b-treated control group." (PMID 36776848, 2023). "Levels of IFN-γ, TNF-α, IL-6, and IL-10, which are important for the activation of protective immunity, were significantly increased at the early stage of ΔPbMAP1 infection." (PMID 37563696, 2023).